SELENBP1 (selenium binding protein 1)
Description:
Catalyzes the oxidation of methanethiol, an organosulfur compound known to be produced in substantial amounts by gut bacteria. Selenium-binding protein which may be involved in the sensing of reactive xenobiotics in the cytoplasm. May be involved in intra-Golgi protein transport (By similarity).
Synonyms: MTO; SBP56; SP56; hSP56; hSBP; LPSB; EHMTO; HEL-S-134P
Tractability: Antibody: UniProt places it where antibodies can reach, with medium confidence. PROTAC: ubiquitination databases record sites on it; its protein half-life has been measured.
Gene: Protein-coding gene on chromosome 1 (151,364,302 to 151,372,716, reverse strand). Ensembl gene ENSG00000143416.
Subcellular location: Nucleus; Cytoplasm, cytosol; Membrane
Subcellular location (Human Protein Atlas): Nucleoli
Gene Ontology:
Molecular function: methanethiol oxidase activity; protein binding; selenium binding
Cellular component: extracellular exosome; extracellular region; nucleolus; nucleus; membrane; cytosol
Genetic constraint (gnomAD): Loss-of-function variants: 71 observed, 61.84 expected, observed/expected ratio (o/e) 1.15, 90% interval 0.95 to 1.4. The upper end of that interval is the gene's LOEUF score, 1.4, which puts it in group 5 of 6, group 1 being the genes least tolerant of losing a copy. Missense variants: 561 observed, 625.77 expected, observed/expected ratio (o/e) 0.9, 90% interval 0.84 to 0.96. Synonymous variants: 270 observed, 247.28 expected, observed/expected ratio (o/e) 1.09, 90% interval 0.99 to 1.21.
Gene-disease validity (ClinGen):
ClinGen rates the evidence that SELENBP1 causes each of these diseases.
extraoral halitosis due to methanethiol oxidase deficiency (autosomal recessive): Moderate.
Homologues: Orthologues: chimpanzee SELENBP1 (99% identical), macaque SELENBP1 (99% identical), pig SELENBP1 (93% identical), dog SELENBP1 (92% identical), rabbit SELENBP1 (90% identical), rat Selenbp1 (89% identical), guinea pig SELENBP1 (88% identical), mouse Selenbp1 (88% identical), mouse Selenbp2 (88% identical), tropical clawed frog selenbp1 (76% identical), zebrafish selenbp1 (75% identical), Drosophila melanogaster CG7966 (53% identical), and 2 more.
Diseases named in the same sentence as SELENBP1 in open-access papers:
SELENBP1 is named in the same sentence as 111 diseases in open-access papers, as found by Europe PMC text mining. Sharing a sentence is not in itself a finding about the gene and the disease. The quoted sentences say what the papers report.
colorectal cancer (15 papers, 2009 to 2024). A primary or metastatic malignant neoplasm that affects the colon or rectum. "As a member of the family of selenium-binding proteins, SELENBP1 is a tumor suppressor, and its low expression has been reported to contribute to a poor prognosis in the lung, ovarian, and colorectal cancers." (PMID 37964257, 2023). "Selenium-binding protein 1 (SELENBP1) is frequently dysregulated in various malignancies including colorectal cancer (CRC); however, its roles in progression of CRCs and the underlying mechanism remain to be elucidated." (PMID 36117772, 2022). "For this purpose, we analyzed TCGA transcriptome data and divided colorectal cancer samples into high and low SELENBP1 expression groups." (PMID 36253721, 2022). "On the other hand, decreases in SELENBP1 levels have been reported for many types of cancer, including colorectal carcinomas." (PMID 33901808, 2021). "DNA methylation has been recognized as a major mechanism responsible for epigenetic silencing of SELENBP1 expression in esophageal and colorectal cancer." (PMID 31918717, 2020). "In line with prior reports in esophageal and colorectal cancer, DNA methylation in the immediate vicinity of the TSS is inversely associated with SELENBP1 expression (Pearson correlation coefficients ranging from − 0.339 to − 0.505; p < 0.001)." (PMID 31918717, 2020). "Some evidence has shown that decreased SELENBP1 in lung and colorectal cancer is related to poor prognosis and increased expression level in zebrafish heart, and can be used as a biomarker of aging." (PMID 31828104, 2019). "Silencing of the SELENBP1 gene due to hypermethylation and chromatin remodeling appears to be frequently involved in tumorigenesis of colorectal cancer." (PMID 29535818, 2018). "Based on this we focused on the role of SELENBP1 in colorectal cancer to investigate." (PMID 36253721, 2022). "Previous studies have only focused on the significant decrease or even disappearance of SELENBP1 expression levels in most cancer tissues like prostate, ovarian, lung, and colorectal cancers, and closely correlated with tumor prognosis, but the mechanisms have not been explored." (PMID 36253721, 2022). "This indicates that reduced SELENBP1 expression may correlate with tumor progression in later stages in the pathogenesis of breast cancer, as is the case with colorectal cancer." (PMID 23704933, 2013). "However, it is currently lacking research about relationship between SELENBP1 and immunotherapy in colorectal cancer (CRC)." (PMID 36253721, 2022). "Moreover, SELENBP1 positively correlated with eosinophils, B cells, and Th17 cells, and negatively correlated with macrophages, Th1 cells, neutrophils, Th2 cells, Tgd, NK cells, T helper cells, Tem, cytotoxic cells, Tcm, CD8 T cells, aDC and DC in patients with colorectal cancer." (PMID 39728443, 2024). "SELENBP1 can also inhibit CRC through lipid/glucose metabolic signaling pathways and participate in mitochondrial function in the HCT116 human colorectal carcinoma cell line through cysteine 57 in SELENBP1." (PMID 36386843, 2022).
schizophrenia (14 papers, 2010 to 2024). A major psychotic disorder characterized by abnormalities in the perception or expression of reality. "Hence, deficiency of SELENBP1 causes deficiency of selenium, leading to certain neurologic diseases such as recent-onset schizophrenia and autism." (PMID 36761165, 2022). "However, no study has demonstrated a causal genetic link between increased PFC SELENBP1 expression and schizophrenia." (PMID 36512497, 2022). "We therefore hypothesized that CNV including the SELENBP1 locus is associated with schizophrenia." (PMID 20615253, 2010). "Hence, rare reduction in SELENBP1 CNVs associates with schizophrenia providing proof of concept for our working hypothesis." (PMID 20615253, 2010). "In the brain, higher expression is observed in the PFC of schizophrenia patients 51, while higher circulating SELENBP1 protein is an adverse biomarker for both traumatic and acute coronary syndrome 52,53." (PMID 38343831, 2024). "A subsequent study analyzing gene expression in specific brain regions of patients with schizophrenia reported SELENBP1 upregulation in the prefrontal cortex (PFC)." (PMID 36512497, 2022). "The relative expression levels of SELENBP1 transcripts in patients with schizophrenia were higher than those in controls (primer set #1, t t5 = 2.05, P < 0.05, one-sample t test, one-tailed), consistent with previous findings." (PMID 36512497, 2022). "Previous gene expression analyses of postmortem samples from patients with schizophrenia revealed increased SELENBP1 expression in the PFC." (PMID 36512497, 2022). "To replicate earlier finding on the SELENBP1 upregulation in the PFC region of patients with schizophrenia, we measured expression levels of SELENBP1 transcripts in postmortem Brodmann area 9 (BA9) of patients with schizophrenia." (PMID 36512497, 2022). "Schizophrenia-like behaviors in hSELENBP1 Tg mice and mice expressing Selenbp1 in the FC were assessed." (PMID 36512497, 2022). "SELENBP1 transcript levels were higher in the brains of patients with schizophrenia than in those of matched healthy controls." (PMID 36512497, 2022). "Here, we examined the anatomical deformities, physiological properties, electroencephalographic characteristics of the frontal cortex, and behaviors of animal models overexpressing human SELENBP1 to prove the role of SELENBP1 in schizophrenia pathogenesis." (PMID 36512497, 2022). "Selenium-binding protein 1 (SELENBP1) is up-regulated in the prefrontal cortex of patients with schizophrenia as per postmortem reports, including the present study." (PMID 36512497, 2022). "The selenium-binding protein 1 (SELENBP1) has been reported to be up-regulated in the prefrontal cortex (PFC) of schizophrenia patients in postmortem reports." (PMID 36512497, 2022). "We verified the levels of SELENBP1 transcripts in postmortem PFC brain tissues from patients with schizophrenia and matched healthy controls." (PMID 36512497, 2022). "We verified these findings, demonstrating increased SELENBP1 levels in the PFC of patients with schizophrenia compared with those of controls across diverse demographic and postmortem factors, including sex, race, age, PMI, and tissue pH." (PMID 36512497, 2022). "To determine the relationship between increased SELENBP1 expression and schizophrenia-like endophenotypes, we generated Tg mice carrying human SELENBP1 and characterized them neuroanatomically, electroencephalographically, and behaviorally." (PMID 36512497, 2022). "Postmortem neurochemical investigations of patients with schizophrenia, including those reported in the present study, imply an association between increased PFC SELENBP1 expression and schizophrenia development." (PMID 36512497, 2022). "In this regard, up-regulated expression of SELENBP1 has been reported in both blood and brain of schizophrenic patients resulting a strong candidate biomarker for schizophrenia." (PMID 27518164, 2016).
schizophrenia (continued). "Previous studies have performed comparative gene expression analysis between brain tissues and peripheral blood samples of schizophrenia patients and demonstrated concurrent up-regulation of SELENBP1 which was proposed as a candidate biomarker for SZ." (PMID 27661005, 2016). "In BA9, SELENBP1 mRNA was significantly higher in subjects with schizophrenia (4.20±0.47) compared with control (2.36±0.25; t58=3.47, P=0.001)." (PMID 26241353, 2015). "Findings from other studies indicate that there are altered SELENBP1 protein levels in subjects with schizophrenia." (PMID 26241353, 2015). "In a comparative blood and brain gene expression study we demonstrated that the gene for selenium binding protein-1 (SELENBP1) was upregulated in both compartments in schizophrenia and was validated in the blood using qRT-PCR and immunohistochemistry." (PMID 23805071, 2013). "In a follow-up qRT-PCR study looking at a separate brain cohort, our group also observed increased SELENBP1 expression in the dlPFC of patients with schizophrenia." (PMID 23805071, 2013). "A reduction in SELENBP1 mRNA levels in the postmortem cerebellar samples of schizophrenia patients was found." (PMID 20615253, 2010). "Since CNV varies among tissues we then studied SELENBP1 CNV in postmortem cerebellum of schizophrenia patients and unrelated matched controls." (PMID 20615253, 2010). "This qualitative phenomenon did not reflect an overall significant difference in the distribution of normalized Ct values of the SELENBP1 locus between the schizophrenia patients and the healthy controls." (PMID 20615253, 2010). "We analyzed SELENBP1 CN variation (CNV) in blood DNA from 49 schizophrenia patients and 49 controls (cohort A)." (PMID 20615253, 2010). "In the postmortem brain specimens (cohort B) a markedly reduced copy number of SELENBP1 in two schizophrenia specimens was observed." (PMID 20615253, 2010). "In summary, because human SELENBP1 is a highly conserved protein, social-behavioral impairments in both Tg mice carrying the human SELENBP1 gene and mice transduced with SELENBP1 into the FC provide clinical and molecular clues to understand the role of SELENBP1 in schizophrenia development." (PMID 36512497, 2022). "Hence, neuropathological and behavioral characterization of animals overexpressing cell-type specific SELENBP1 would more clearly define the role of SELENBP1 and provide clues to reveal its mechanism in schizophrenia." (PMID 36512497, 2022). "Selenium binding protein 1 (SELENBP1) was an important selenoprotein and was suggested that genetic variation in SELENBP1 may influence the risk for schizophrenia." (PMID 36082036, 2022). "However, both downregulation and upregulation of plasma SELENBP1 in schizophrenia patients have also been reported in the other two studies." (PMID 36082036, 2022). "SELENBP1 has been suggested to play a role in the development of schizophrenia; however, the mechanism remains unknown, largely because SELENBP1 is not robustly expressed in the brains of adult humans and rodents." (PMID 36512497, 2022). "Although SELENBP1 upregulation has been reported in multiple postmortem schizophrenia studies, its functional role in brain remains unclear." (PMID 31060314, 2019). "Selenium-binding protein-1 (SELENBP1) is involved in selenium transport, an essential nutrient which displays neuroprotective and antioxidant activities in preventing certain neurologic diseases, such as schizophrenia and bipolar disorder." (PMID 27518164, 2016). "Genes previously showing strong genetic evidence implicated in schizophrenia identified in this study include: regulator of G-protein signaling 4 (RGS4); discoidin domain receptor family, member 1(DDR1); and the selenium binding protein 1(SELENBP1)." (PMID 26818902, 2016). "To challenge this hypothesis, we investigated whether SELENBP1 is differentially expressed in the cortex from subjects with schizophrenia, BP or major depressive disorder (MDD)." (PMID 26241353, 2015).
schizophrenia (continued). "Our findings of higher levels of SELENBP1 mRNA in the dorsolateral prefrontal cortex of subjects with schizophrenia are in agreement with previous studies, and we further show that these changes are likely to be widespread throughout the cortex of subjects with the disorder." (PMID 26241353, 2015). "In contrast to these findings, a study of 30 patients first hospitalized for a psychotic episode with symptoms consistent with schizophrenia (n = 15), schizophreniform disorder (n = 13) or schizoaffective disorder (n = 2) investigated levels of SELENBP1 in PBCs after commencement of treatment." (PMID 23805071, 2013). "Given that reductions in synaptic and dendritic arbors have been observed in the brains of patients with schizophrenia, elevated SELENBP1 may play a compensatory role in restoring neuronal connectivity and functioning." (PMID 23805071, 2013). "While increased expression of SELENBP1 in the dlPFC in schizophrenia may be present, the functional relevance of this upregulation remains to be elucidated." (PMID 23805071, 2013). "Since CNV may either be de-novo or inherited we analyzed CNV of the SELENBP1 locus in blood DNA from 26 trios of schizophrenia probands and their healthy parents (cohort C)." (PMID 20615253, 2010). "Since CNV may either be de novo or inherited we further analyzed CNV of the SELENBP1 gene in trios of schizophrenia probands and their healthy parents in whole blood DNA." (PMID 20615253, 2010). "In order to find out whether CNV in the SELENBP1 locus associates with the previously reported up-regulation of brain SELENBP1 in schizophrenia, we measured SELENBP1 mRNA levels in the same postmortem cerebellar specimens studied for CNV." (PMID 20615253, 2010). "Moreover, SELENBP1 mRNA levels were up-regulated in postmortem brain and in blood cells from schizophrenia patients." (PMID 20615253, 2010). "Furthermore, given the involvement of various genetic determinants in highly heritable brain disorders, such as schizophrenia and ASD, as demonstrated by genome-wide association studies, we examined CNVs and relevant loci in PFC tissues of two patients with schizophrenia with up-regulated SELENBP1." (PMID 36512497, 2022). "However, there has been no causal link between SELENBP1 upregulation and the manifestation of diverse schizophrenia symptoms." (PMID 36512497, 2022). "In addition, SELENBP1 mRNA levels are increased in the PFC of patients with schizophrenia." (PMID 36512497, 2022). "These analyses identified overlapping CNVs in lncRNAs of the ASD-related genes, HERC2, and GOLGA8, in the 15q11.1—11.2 schizophrenia/ASD-associated duplication region, suggesting that the pathogenesis of SELENBP1 upregulation in schizophrenia may be related to that of ASD." (PMID 36512497, 2022). "Thus, it is expected that increased SELENBP1 expression in the brain could produce an excess of sulfur-containing compounds and induce schizophrenia-like abnormalities in behavior and cellular morphology, a possibility that warrants further investigation." (PMID 36512497, 2022). "Schizophrenia and bipolar disorder are characterized by an elevated level of selenium binding protein 1 (SELENBP1) gene expression; however, it is yet unclear whether enhanced expression of SELENBP1 correlates with a higher incidence of psychosis." (PMID 33334078, 2020). "Thus, a more detailed examination of SELENBP1 protein in the CNS could reveal a physiological outcome of upregulated mRNA in schizophrenia." (PMID 26241353, 2015). "This supports the notion that SELENBP1 may have a role in the pathophysiology of schizophrenia." (PMID 26241353, 2015). "Since copy number of genes may vary among tissues, we further investigated (Cohort B) SELENBP1 copy number in age- sex- and postmortem interval-matched cerebellar DNA samples from 14 schizophrenia patients and 14 unrelated matched controls originating from the Australian population." (PMID 20615253, 2010).
schizophrenia (continued). "However, no causative link between SELENBP1 and schizophrenia has yet been established." (PMID 36512497, 2022). "SELENBP1 mRNA was higher in BA9 (P=0.001), BA8 (P=0.003) and BA44 (P=0.0007) from subjects with schizophrenia." (PMID 26241353, 2015). "Selenium binding protein 1 (SELENBP1) messenger RNA (mRNA) has previously been shown to be upregulated in the brain and blood from subjects with schizophrenia." (PMID 26241353, 2015). "Additionally, we examined the attentional status of DsRed2 controls and mice with FC-transduced Selenbp1 mice using the attentional set-shifting task (ASST), a behavioral task for measuring cognitive symptoms in schizophrenia animal models." (PMID 36512497, 2022). "A study of patients during their first hospitalization with schizophrenia did not report different levels of SELENBP1 mRNA in blood compared with controls." (PMID 36082036, 2022). "Here, we provide evidence linking the upregulation of SELENBP1 in the PFC of mice with the negative symptoms of schizophrenia." (PMID 36512497, 2022). "We also generated and characterized Tg mice expressing human SELENBP1 (hSELENBP1), showing that these mice displayed brain correlates of schizophrenia and behavioral phenotypes characteristic of the negative symptoms of schizophrenia." (PMID 36512497, 2022). "SELENBP1 mRNA was also higher in subjects with schizophrenia in BA44 (2.01±0.16 schizophrenia, 1.25±0.15 control; t58=3.57, P=0.0007) and BA8 (1.77±0.17 schizophrenia, 1.04±0.15 control; t58=3.15, P=0.003)." (PMID 26241353, 2015). "With this study, it has now been shown in three separate cohorts that SELENBP1 mRNA is upregulated in the frontal cortex of subjects with schizophrenia, an effect not attributed to antipsychotic medication." (PMID 26241353, 2015). "Our data show that elevated SELENBP1 transcript expression is widespread throughout the prefrontal cortex in schizophrenia, and confirm that this change is a consistent feature of schizophrenia and not a simple drug effect." (PMID 26241353, 2015). "Interestingly, the expression of SELENBP1 was significantly correlated with psychosis in a combined sample of schizophrenia and bipolar disorder patients regardless of their diagnosis." (PMID 23805071, 2013).